PTH (parathyroid hormone)
Diseases named in the same sentence as PTH in open-access papers (continued):
Sharing a sentence is not in itself a finding about the gene and the disease.
Hypocalcemia (continued). "The female proband in family B, the first child of first-degree cousins originally from Southern Turkey, presented with seizures because of profound hypocalcemia at the age of 2 mo associated with an elevated PTH level, yet no hypophosphatemia." (PMID 36795755, 2023). "Otherwise, the effect of parathyroid dysfunction and peripheral resistance to PTH, both induced by cytokines, are other potential explanations for hypocalcemia occurrence, as reported in literature, and for PTH having been resulted not significantly dissimilar between categories of calcium." (PMID 36350462, 2023). "From this figure, we can conclude that the level of serum PTH can predict hypocalcemia and may be a good predictive factor in controlling calcium levels in RA patients." (PMID 37849009, 2023). "In the literature review pertaining to adolescent PHPT, following the successful resection of hyperparathyroidism, the parathyroid hormone level can be reduced by more than 50%, but patients were prone to hypocalcemia, rapid decline of calcium level and/or spasm." (PMID 37807045, 2023). "Also, over-suppressed PTH level was the reason in two patients, as well as hypocalcemia and possible allergic reaction in one patient each." (PMID 38050530, 2023). "PTH was 11 pg/mL and calcium was 2.16 mmol/L, suggesting impending transient hypocalcemia." (PMID 37080143, 2023). "The aim of this study was to retrospectively determine whether in dogs with primary hyperparathyroidism, pre‐treatment serum PTH concentration can be used to predict development and/or severity of post‐surgical treatment hypocalcemia." (PMID 38053473, 2023). "Studies on the effect of selected risk factors on hypocalcemia were summarized in meta-analyses, which confirmed that the most significant factor in the occurrence of postoperative hypocalcemia was a decrease in PTH levels due to intraoperative parathyroid injury." (PMID 37626794, 2023). "In multivariate analysis, female sex, neck dissection, incidental parathyroidectomy, and PTH levels < 12 pg/mL were predictive of postoperative temporary hypocalcemia, while age did not relate to an increased risk of hypocalcemia." (PMID 36902740, 2023). "Additionally, these results should also be translatable to humans where a relationship between hypocalcemia and hypomagnesemia is also known but yet explained solely via decreased secretion or action of PTH at low Mg2+ concentrations." (PMID 37240030, 2023). "Hypoparathyroidism is characterized by hypocalcemia owing to insufficient PTH secretion." (PMID 36123043, 2023). "Hypocalcemia commonly results from disorders of parathyroid hormone (PTH) and vitamin D." (PMID 37501199, 2023). "Once hypocalcemia is confirmed, PTH levels should be measured." (PMID 37251665, 2023). "Therefore, the specific mechanisms underlying hypocalcemia may involve vitamin D acting as a steroid hormone in immune regulation, changes in intestinal calcium absorption, decreased serum albumin levels, reduced calcium influx, and decreased parathyroid hormone secretion." (PMID 38145047, 2023). "In addition to severe hypocalcemia, he was found to have an inappropriately low serum parathyroid hormone level and basal ganglia calcifications visualized on head computed tomography scan." (PMID 37908569, 2023). "Change in post operative PTH has NPV of 91% in predicting symptomatic hypocalcemia." (PMID 37636752, 2023). "In addition, she required calcium supplementation because of severe hypocalcemia, and the blood level of intact parathyroid hormone (PTH) was always below the lower limit." (PMID 36645181, 2023). "The strategy of limiting prepartum dietary Ca through forage quality selection in a positive DCAD diet to prevent clinical hypocalcemia requires reduction of dietary Ca to below maintenance requirements, stimulating parathyroid hormone (PTH) release and Ca mobilization from labile bone stores." (PMID 38045892, 2023).
Hypocalcemia (continued). "Hungry bone syndrome (HBS), severe hypocalcemia following parathyroidectomy (PTX) due to rapid drop of PTH (parathormone) after a previous long term elevated concentration in primary (PHPT) or renal hyperparathyroidism (RHPT), impairs the outcome of underlying parathyroid disease." (PMID 37296804, 2023). "In our study we analysed whether preoperative Vitamin D and 4 hour post operative PTH can reliably predict hypocalcemia in post operative period." (PMID 37636752, 2023). "In addition, data suggest that variable degrees of PTH-resistant hypocalcaemia can occur despite identical epigenetic changes." (PMID 37854194, 2023). "Three patients with symptomatic hypocalcemia had much elevated plasma levels of PTH when measured by intact PTH immunoassay, but low or undetectable levels in biointact PTH assays, thus supporting the diagnosis of either pseudohypoparathyroidism or hypoparathyroidism." (PMID 36795755, 2023). "Intact serum PTH levels were effective in predicting hypocalcemia in RA patients." (PMID 37849009, 2023). "The occurrence of postoperative hypocalcemia was significantly correlated with the decrease of parathyroid hormone (PTH) after surgery; therefore, the baseline preoperative PTH level may be crucial." (PMID 37288589, 2023). "PTH production is increased in AKI due to hypocalcemia and low circulating 1,25D, stimulating the secretion of PTH, which both, when in normal range, cause negative feedback on the parathyroid glands." (PMID 36899104, 2023). "Therefore, a low calcium and phosphate intake, and hypocalcemia, with the consequent rise of PTH, result in active vitamin D production." (PMID 37761831, 2023). "Regarding the 6 patients with POD1 PTH ≥ 15 pg/ml and calcium ≥ 2.0 mmol/l who went on to develop symptomatic hypocalcaemia, 3 were undergoing surgery for Graves disease, one had a history of Graves disease, and one was undergoing surgery for non-Graves hyperthyroidism." (PMID 35247092, 2022). "However, we found no direct relationship between intraoperative parathyroid imaging grade and postoperative hypocalcemia or decreased PTH levels." (PMID 36439530, 2022). "However, not all authors are in agreement that a single postoperative PTH level is sufficient to exclude significant hypocalcaemia." (PMID 35247092, 2022). "Low serum Mg level inhibits hypocalcemia-induced PTH release." (PMID 36589976, 2022). "Blood testing showed severe hypocalcemia and elevated PTH level." (PMID 36465610, 2022). "We think it is possible that hypocalcemia due to vitamin D deficiency increases PTH levels through negative feedback, leading to a decrease in IP." (PMID 35029240, 2022). "Authors hypothesised that the early state of hypocalcaemia was due to the high-dose glucocorticoids required for induction, in addition to the preoperative undetectable PTH." (PMID 36672533, 2022). "Since patients with 22q11DS may have reduced PTH reserves and lack appropriate PTH responses to hypocalcemia, perioperative GC administration may contribute to postoperative hypocalcemia in this population." (PMID 36292790, 2022). "The lack of PTH in patients with HypoPT profoundly changes calcium homeostasis and patients are at risk of hypocalcaemia, hypercalciuria, hyperphosphatemia and abnormal skeletal mineralization." (PMID 35751804, 2022). "Even if patients' PTH levels are within the normal range following surgery, some patients may experience episodes of hypocalcemia and require replacement medication at any time." (PMID 36644104, 2022). "However, low vitamin D levels reduce calcium absorption, upregulating parathyroid hormone release, osteoclastogenesis, and bone resorption to prevent hypocalcemia." (PMID 36618706, 2022). "Therefore, intact Dicer and miRNAs are essential for activation of the parathyroid by the major stimuli for PTH secretion, acute and chronic hypocalcemia and uremia." (PMID 35208186, 2022). "PTH acts in the kidney, intestine and bone, replenishing serum calcium during hypocalcemia." (PMID 36359775, 2022).
Hypocalcemia (continued). "A predictive model constructed using a combination of preoperative PTH, Ca, and ALP may represent a useful means of identifying patients with SHPT at high risk of developing hypocalcemia following PTX in clinical practice." (PMID 36531501, 2022). "The associations of eight factors (age, sex, PTH, Ca, IP, ALP, the number of parathyroid glands resected, and the presence of ectopic parathyroid tissue) with the development of hypocalcemia following PTX in patients with SHPT were assessed in the present study." (PMID 36531501, 2022). "When hypocalcemia is detected, magnesium, phosphate, 25-OH-vitamin D, and PTH should be assessed." (PMID 36149449, 2022). "The mechanisms of hypocalcemia in SAP may be multi-factorial, such as abnormalities of parathyroid hormone secretion and action as well as vitamin D deficiency, binding of calcium in areas of fat necrosis, likely to contribute to the medication side effects." (PMID 35755843, 2022). "Early parathyroid hormone (PTH) levels after total thyroidectomy can predict patients at low risk of hypocalcaemia who can be discharged early without calcium supplementation." (PMID 35247092, 2022). "This revealed that patients with PTH resistance, such as P3, may present with hyperphosphatemia, hypocalcemia, and muscle weakness." (PMID 35296306, 2022). "Our study confirmed that patients with a history of restrictive bariatric surgery have no increased risk for hypocalcemia and hypo-PTH after TT." (PMID 35565776, 2022). "The main endocrine associated disorders—diabetes mellitus, acromegaly and hypoparathyroidism—are characterized by disturbances in the metabolism of glucose, growth hormone (GH), and parathyroid hormone (PTH), leading to hypocalcemia, hyperphosphatemia, hyperglycemia and hyperinsulinemia." (PMID 36276944, 2022). "Finally, Kosec reported a POD1 PTH level < 2.9 pmol/l (equivalent to 27 pg/ml) to predict hypocalcaemia on the fifth postoperative day, which was similar to the optimal 1-h postoperative cut-off (< 2.99 pmol/l)." (PMID 35247092, 2022). "Although the exact mechanism of magnesium-calcium interaction is unknown, hypomagnesemia generally impairs the secretion of parathyroid hormone or increases resistance to parathyroid hormone, leading to hypocalcemia." (PMID 36424547, 2022). "However, the lower their PTH concentration is following surgery, the greater is their calcium and phosphorus deposition in bone, and the more likely it is that hypocalcemia will occur." (PMID 36531501, 2022). "As hypocalcemia develops, the CaMs should be discontinued, and the vitamin D or vitamin D analog could be the agent lowering the PTH." (PMID 36015101, 2022). "Both of them had lowered PTH levels and symptoms of hypocalcaemia on POD1." (PMID 35683589, 2022). "Our study first specifically evidenced that patients previously submitted to restrictive bariatric surgery (GB and LSG) were no exposed to higher risk of post-operative hypocalcemia and hypo-PTH than matched patients without a history of bariatric surgery." (PMID 35565776, 2022). "KCS patients are characterized by hypoparathyroidism and hypocalcemia; low calcium levels have also been detected in OCS cases, supporting the hypothesis of a PTH dysfunction underlying both conditions." (PMID 35205306, 2022). "PHP is characterized by hypocalcemia, hyperphosphatemia and elevated serum PTH levels." (PMID 35410271, 2022). "Meanwhile, it has been observed that increased P levels may induce hypocalcemia, which increases PTH secretion, and directly stimulate PTH synthesis and parathyroid cellular proliferation." (PMID 36079837, 2022). "At the same time, it will damage the recurrent laryngeal nerve and parathyroid gland, resulting in insufficient secretion of parathyroid hormone, lowering of blood calcium content, and even inducing hypocalcemia convulsion, which seriously affecting the postoperative recovery quality." (PMID 35722535, 2022).
Hypocalcemia (continued). "Hypoparathyroidism is a rare endocrine disease characterized by hypocalcemia associated with hyperphosphatemia and concomitant absent or inappropriately low levels of parathyroid hormone (PTH)." (PMID 36382754, 2022). "Blood testing showed hypocalcemia, high PTH level, and normal kidney/liver function." (PMID 36465610, 2022). "Laboratory tests revealed hypocalcemia, normal serum phosphate, and elevated serum PTH." (PMID 35871092, 2022). "Hypocalcemia is associated with low FGF23 levels as a study of Gcm2−/− mice characterized by hypocalcemia, hyperphosphatemia, and low calcitriol and PTH levels and Cyp27b1−/− mice with hypocalcemia, hypophosphatemia, and low 1,25(OH)2D3 but high PTH levels has revealed." (PMID 35084563, 2022). "The higher the PTH concentration in the preoperative period, the more profound the hypocalcemia." (PMID 36268338, 2022). "When PTH-driven demineralization of the skeleton cannot further compensate calcium deprivation, patients may present with symptomatic hypocalcemia, i.e., seizures and tetany and heart failure due to dilated cardiomyopathy in infants." (PMID 34910242, 2022). "The higher the PTH concentration in the preoperative period, the deeper the hypocalcemia." (PMID 36268338, 2022). "Hypothesized pathophysiology of hypocalcemia in critically ill animals includes calcium binding by excess phosphorus, parathyroid hormone resistance, and acid-base alterations." (PMID 35450137, 2022). "However, patients who presented postoperative hypocalcemia had significantly lower PTH and Calcium 10 min and 4 h after surgery." (PMID 35566513, 2022). "When taking them together, a mean reduction of PTH levels of 73 ± 11 per cent was observed in the patient cohort that developed hypocalcaemia, whereas the group of patients with a mean reduction of PTH levels of 39.5 ± 7.3 per cent had no hypocalcaemia in the following course (P < 0.0001)." (PMID 36050906, 2022). "Hypocalcemia is considered to be the main stimulus of PTH synthesis from parathyroid glands." (PMID 36142318, 2022). "Serum PTH levels were inappropriately low in the setting of hypocalcemia." (PMID 35663648, 2022). "Furthermore, PTH-triggered “osteocytic osteolysis” enables rapid serum calcium replenishment in hypocalcemia." (PMID 36359775, 2022). "Whereas the development of hypocalcemia is a further stimulation for PTH secretion, excessive positive calcium balance may increase the risk for ectopic calcifications and cardiovascular risk." (PMID 34371838, 2021). "Our study aims to find out if an early reduction of PTH after TT can predict hypocalcemia." (PMID 34429957, 2021). "A recent statement on hypoparathyroidism of the American Thyroid Association found that the timing of PTH measurements in published studies has ranged from 10 min to 24 h post-thyroidectomy, and that a postoperative PTH level < 15 pg/mL is usually predictive of hypocalcemia." (PMID 34575224, 2021). "A decrease in PTH levels may induce a clinically detectable hypocalcemia delayed for up to 48 h after the hypoparathyroidism." (PMID 34574074, 2021). "PTH <15 pg/mL at 3 h after total thyroidectomy accurately predicts post-operative hypocalcemia." (PMID 34574074, 2021). "PTH resistance is the detection of increased PTH serum levels, hypocalcemia and hyperphosphatemia in the absence of vitamin D deficiency and in the presence of normal magnesium levels and normal renal function." (PMID 33179219, 2021). "Moreover, our experimental group also exhibited hypocalcemia and thus the elevation of serum PTH, leading to a decline in OPG levels." (PMID 33637698, 2021). "In addition to routine parameters, serum calcium and PTH concentrations should be checked every 2 weeks, and postoperative medication should be adjusted to avoid hypocalcemia." (PMID 34420520, 2021).
Hypocalcemia (continued). "Accordingly, early detection of hypocalcemia after thyroidectomy within the same day of operation is almost impossible due to the fact that PTH is well known to be a useful indicator of impending post-thyroidectomy hypocalcemia, rapid PTH assay has been used to measure intraoperative PTH levels." (PMID 34429957, 2021). "When animals show symptoms of hypomagnesemia, parathyroid hormone will be insufficiently produced and hypocalcemia could be further aggravated, because Mg is required for the secretion of parathyroid hormone." (PMID 34573507, 2021). "HypoPT following anterior neck surgery (mostly thyroid and less frequently parathyroid surgery) is suspected in patients with symptomatic or asymptomatic hypocalcemia and low PTH concentrations, or inappropriately normal PTH concentrations despite hypocalcemia." (PMID 34863037, 2021). "Blood work revealed markedly elevated PTH at 3,563 pg/mL, hypocalcemia, and hyperphosphatemia." (PMID 34540402, 2021). "PTH levels may be variable and increased at times as part of a normal feedback response to low vitamin D levels and subsequently hypocalcemia." (PMID 33191899, 2021). "Lower baseline pre-RAI serum calcium and PTH levels and negative 99mTcO4- thyroid imaging were risk factors for hypocalcemia five days post-RAI." (PMID 34122347, 2021). "Hypocalcemia stimulates PTH secretion, which activates vitamin D synthesis." (PMID 34113519, 2021). "However, clinical outcome was distinctly different between Groups C and D, namely, in clinical hypocalcemia, i.v. calcium requirement, and long-term PTH level at 6 and 12 months after surgery." (PMID 33762946, 2021). "The p.Asn502His variant showed a reduction in transactivation and it was found in the heterozygous state in one patient diagnosed at 5 days of age, presenting with hypocalcemia, hyperphosphatemia, hypomagnesemia, low 25-OH vitamin D levels and normal serum intact PTH levels." (PMID 33536578, 2021). "Causes of hypocalcemia with PTH elevation include increased phosphate load, vitamin D deficiency (VDD) or defects in metabolism, renal dysfunction, hypomagnesemia, genetic mutations resulting in end-organ resistance to PTH, or critical illness." (PMID 34194851, 2021). "PTH levels on the first postoperative day predict temporary hypocalcemia and HypoPT." (PMID 34863037, 2021). "Furthermore, a decrease in parathyroid hormone levels within the first 24 hours following surgery was a statistically significant predictor of developing post-thyroidectomy hypocalcemia (P < 0.001)." (PMID 34987897, 2021). "In this study, serum PTH drawn 3 h after surgery was predictive of subsequent hypocalcemia." (PMID 34574074, 2021). "Hypocalcemia, hypomagnesemia, lymphocytopenia, thrombocytopenia, and abnormalities of the thyroid, parathyroid hormone or vitamin D levels may remain undiscovered in 22q11.2 deletion patients, especially without genetic diagnosis." (PMID 33995479, 2021). "Moreover, if the post-operative parathyroid hormone level dropped to 6-35 pg/mL within one hour to one day after surgery, the chance of developing temporary post-thyroidectomy hypocalcemia reached 69-100%." (PMID 34987897, 2021). "Consequently, all these factors must be considered in order to prevent post-thyroidectomy hypocalcemia, while PTH evaluation should remain a marker for starting calcium and vitamin D supplementation after surgery." (PMID 34574074, 2021). "The resulting hypocalcaemia is exacerbated by an immature newborn PTH-response." (PMID 33614549, 2021). "Patients with end-stage renal disease (ESRD) may demonstrate secondary hyperparathyroidism (SHPT), characterized by parathyroid hormone oversecretion in response to electrolyte imbalance (e.g., hypocalcemia and hyperphosphatemia)." (PMID 33436789, 2021). "Multivariate regression analysis showed that baseline pre-RAI serum calcium < 2.27 mmol/L, PTH < 4.18 pmol/L and negative 99mTcO4- thyroid imaging were risk factors for hypocalcemia at five days post-RAI." (PMID 34122347, 2021).